TIMMDC1 (translocase of inner mitochondrial membrane domain containing 1)
Description:
Chaperone protein involved in the assembly of the mitochondrial NADH:ubiquinone oxidoreductase complex (complex I). Participates in constructing the membrane arm of complex I.
Synonyms: C3orf1; FLJ22597; MC1DN31
Tractability: Antibody: UniProt predicts a signal peptide or a membrane-spanning region. PROTAC: ubiquitination databases record sites on it; its protein half-life has been measured.
Gene: Protein-coding gene on chromosome 3 (119,498,515 to 119,525,090, forward strand). Ensembl gene ENSG00000113845.
Subcellular location: Mitochondrion membrane
Subcellular location (Human Protein Atlas): Mitochondria; Nucleoplasm
Pathways (Reactome):
Metabolism: Complex I biogenesis
Gene Ontology:
Molecular function: protein binding
Biological process: mitochondrial respiratory chain complex I assembly
Cellular component: mitochondrion; nucleoplasm; mitochondrial inner membrane; mitochondrial membrane
Genetic constraint (gnomAD): Loss-of-function variants: 21 observed, 29.56 expected, observed/expected ratio (o/e) 0.71, 90% interval 0.5 to 1.02. The upper end of that interval is the gene's LOEUF score, 1.02, which puts it in group 4 of 6, group 1 being the genes least tolerant of losing a copy. Missense variants: 277 observed, 304.19 expected, observed/expected ratio (o/e) 0.91, 90% interval 0.82 to 1.01. Synonymous variants: 109 observed, 112.53 expected, observed/expected ratio (o/e) 0.97, 90% interval 0.83 to 1.14.
Gene-disease validity (ClinGen):
ClinGen rates the evidence that TIMMDC1 causes each of these diseases.
mitochondrial disease (autosomal recessive): Definitive.
Leigh syndrome (autosomal recessive): Limited. A progressive neurological disease defined by specific neuropathological features associating brainstem and basal ganglia lesions.
Homologues: Orthologues: chimpanzee TIMMDC1 (99% identical), macaque TIMMDC1 (90% identical), rabbit TIMMDC1 (84% identical), pig TIMMDC1 (78% identical), guinea pig TIMMDC1 (74% identical), rat Timmdc1 (72% identical), mouse Timmdc1 (71% identical), dog TIMMDC1 (66% identical), tropical clawed frog timmdc1 (44% identical), zebrafish timmdc1 (43% identical), Drosophila melanogaster 140up (25% identical), Caenorhabditis elegans Y38F2AR.3 (18% identical).
Diseases named in the same sentence as TIMMDC1 in open-access papers:
TIMMDC1 is named in the same sentence as 16 diseases in open-access papers, as found by Europe PMC text mining. Sharing a sentence is not in itself a finding about the gene and the disease. The quoted sentences say what the papers report.
gastric cancer (2 papers, 2014 to 2024). A primary or metastatic malignant neoplasm involving the stomach. "A previous study demonstrated that increased levels of TIMMDC1 can promote gastric cancer proliferation." (PMID 38652547, 2024).
lung carcinoma (2 papers, 2014 to 2024). "In summary, we identified higher expression of C3orf1/TIMMDC1 in 95D lung carcinoma cells and confirmed C3orf1 locals in the inner mitochondrial membrane." (PMID 25391042, 2014). "In our previous study, we identified an association of high expression of c3orf1, also known as TIMMDC1 (translocase of inner mitochondrial membrane domain-containing protein 1), with metastatic characteristics in lung carcinoma cells." (PMID 25391042, 2014). "Additionally, depletion of TIMMDC1 inhibited migration and proliferation in 95D lung carcinoma cells, leading to a marked reduction in mitochondrial viability, membrane potential, and ATPase activity within these cells." (PMID 38652547, 2024). "In our previous study, the human c3orf1 gene, also known as TIMMDC1 (translocase of inner mitochondrial membrane domain-containing protein 1), was identified as being overexpressedin 95D lung carcinoma cells with highly metastatic characteristics by using differential display PCR (ddPCR)." (PMID 25391042, 2014).
asthma (1 paper, 2020). "LncRNA TCF7 was found to be contributed to the growth and migration of ASMCs in asthma through targeting TIMMDC1/Akt axis." (PMID 32929606, 2020).
celiac disease (1 paper, 2019). An autoimmune genetic disorder with an unknown pattern of inheritance that primarily affects the digestive tract. "This locus has also been reported as a susceptibility region for celiac disease, multiple sclerosis, systemic lupus erythematosus, and vitiligo, represented by rs11712165 in ARHGAP31, rs2293370 in TIMMDC1, and rs6804441 and rs148136154 in CD80, respectively." (PMID 30643196, 2019).
Leigh syndrome (1 paper, 2022). "However, homozygosity for the c.847delG (p.Asp283fs+54 aa) TIMMDC1 variant in a patient with Leigh syndrome was shown to have barely detectable TIMMDC1 protein, and thus lower levels of ATP content, mitochondrial respiratory activity and complex I in patient LCLs compared to control cells." (PMID 35091571, 2022).
cancer (2 papers, 2022 to 2024). A tumor composed of atypical neoplastic, often pleomorphic cells that invade other tissues. "Furthermore, a Kaplan-Meier analysis demonstrated that patients with elevated TIMMDC1 expression had significantly shorter cancer-related survival times than those with low TIMMDC1 expression in the TMA cohort (Log-rank test, P = 0.0094)." (PMID 38652547, 2024).
mitochondrial disease (2 papers, 2022 to 2025). "Late detection of assembly factors with severe phenotype includes genes such as NDUFAF3, SURF1, TACO1, SCO1, LYRM7, or TIMMDC1, whose mutations are commonly found in patients with mitochondrial diseases (Fig. EV2F)." (PMID 40301572, 2025).
neurologic disorder (1 paper, 2022). "SSO-mediated therapy of this inevitably fatal TIMMDC1 neurologic disorder is an attractive possibility." (PMID 35091571, 2022).
tumor (1 paper, 2024). "Our results demonstrate that TIMMDC1 knockdown inhibited tumor growth and reduced tumor weights compared with those in the scramble group." (PMID 38652547, 2024). "Moreover, analysis of RNA-Seq data from the TCGA-ESCA cohort revealed significantly increased TIMMDC1 transcript levels in tumor tissues (P < 0.0001)." (PMID 38652547, 2024). "Elevated TIMMDC1 protein levels were observed in most tumor tissues compared with nontumor tissues." (PMID 38652547, 2024).
TIMMDC1 also shares sentences with these, for which no sentence is quoted: esophageal carcinoma (1 paper); lung adenocarcinoma (1); multiple sclerosis (1); ovarian carcinoma (1); Respiratory insufficiency (1); systemic lupus erythematosus (1); vitiligo (1).